STAT3 (signal transducer and activator of transcription 3)
Diseases named in the same sentence as STAT3 in open-access papers (continued):
Sharing a sentence is not in itself a finding about the gene and the disease.
cervical carcinoma (continued). "Furthermore, inhibition of STAT3 activity in cervical cancer cells results in a profound reduction in cellular proliferation and the induction of apoptosis, yet the mechanisms underpinning STAT3 activation and function in this scenario remain unknown." (PMID 31226168, 2019). "Therefore, STAT3-specific inhibitors may be useful for cervical cancer treatment, and various STAT3 inhibitors are in the process of being tested in clinical trials." (PMID 31816985, 2019). "Finally, we demonstrate a correlation between NFκB activation, IL-6 expression and cervical disease progression, suggesting that targeting the IL-6 pathway to prevent STAT3 activation may have therapeutic benefits in cervical cancer." (PMID 31226168, 2019). "Furthermore, we report that TMS-TMF-4f could inhibit the induction of proliferative mediators such as Mcl-1, cyclin D1, survivin, and c-Myc via STAT3 inactivation, subsequently inducing apoptotic cell death in human cervical cancer cells." (PMID 31816985, 2019). "Furthermore, it was reported that the JAK2/STAT3 pathway regulates cervical cancer progression." (PMID 26219895, 2016). "Also, constitutively activated STAT3 has been detected in cervical cancer cells." (PMID 27690342, 2016). "Blocking STAT3 could represent a possible therapeutic strategy in cervical cancer." (PMID 26346346, 2015). "In view of emerging regulatory role of microRNAs, Let-7a and mR-21 that may interact with STAT3 signaling and its downstream effectors, present study was designed in HPV16-positive cervical cancer cells to assess the functional contribution of these miRs in STAT3 signaling in cervical cancer." (PMID 25539644, 2014). "In view of emerging regulatory role of microRNAs, Let-7a and miR-21 that may interact with STAT3 signaling and/or its downstream effectors, present study was designed in HPV16-positive cervical cancer cells to assess the functional contribution of these miRs in STAT3 signaling in cervical cancer." (PMID 25539644, 2014). "Stat3 might be a target of molecular therapy in cervical cancer." (PMID 19638983, 2009). "Therefore, we examined the possible correlation between such parameters and p-Stat3 expression in cervical cancer specimens, and found that p-Stat3 expression significantly correlated with lymph node metastasis, LVSI, and large tumour size (>4 cm) in these patients." (PMID 19638983, 2009). "Since Stat3 activation may play a role in promoting cell growth and survival in cervical and endometrial cancer cells, we subsequently investigated whether the interference of Stat3 activation by transduction of rAd/dnStat3 would affect cell growth or survival of cervical cancer cells in vitro." (PMID 17311011, 2007). "STAT3 is highly expressed in cervical cancer, and the expression of STAT3 protein is positively correlated with TNM stage of cervical cancer, depth of invasion and lymph node metastasis." (PMID 40309242, 2025). "Propofol can suppress cervical cancer cell viability, and enhance cisplatin-mediated apoptosis by inhibiting the EGFR/JAK2/STAT3 pathway, thereby enhancing the anti-tumor effect of cisplatin." (PMID 40309242, 2025). "Previous studies have shown that selenadiazole can suppress tumor growth in cervical cancer cells by elevating intracellular ROS levels and triggering mitochondrial apoptosis through modulation of the JAK2/STAT3 signaling pathway." (PMID 41516206, 2025). "In this study, we found that the STAT3/NF‐κB signaling pathways, along with M2‐TAM, play a crucial role in tumor progression, leading to unfavorable outcomes in 100 patients with cervical cancer." (PMID 41263059, 2025). "In the case of cervical cancer cells, where the integration of HPV genes into the cell genome is additionally observed, STAT3 activation occurs, with tumour-promoting effects." (PMID 40729003, 2025).
cervical carcinoma (continued). "First, to evaluate the interaction between STAT3 and CD204 expression in the TME of cervical cancer (CC) patients, we performed double immunofluorescence staining with anti‐STAT3 and anti‐CD204 antibodies on TMA sections from 100 cervical cancer patients." (PMID 41263059, 2025). "In the microenvironment of cervical cancer, expression levels of B7-H3 and B7-H4 positively correlated with the expression levels of IL-10 and TGF-β1, suggesting correlation with the p-JAK2/STAT3 pathway." (PMID 38850312, 2024). "It has been shown that STAT3 phosphorylation is significantly higher in HPV-positive cervical cancers compared to their HPV-negative counterparts, highlighting the role of HPV in enhancing STAT3 activity." (PMID 39123466, 2024). "In cervical cancer, MACC1 regulates the AKT/STAT3 signaling pathway to induce migration and invasion, but also cancer stemness." (PMID 38339354, 2024). "Breast, ovarian, and cervical cancer, as many other cancers, present elevated IL-6/JAK/STAT3 pathway activity." (PMID 38892394, 2024). "In conclusion, connection between STAT3 and HPV life cycle plays an important role in cervical cancer developing." (PMID 38892394, 2024). "We recently demonstrated that, in cervical cancer cells, STAT1 (Signal Transducer and Activator of Transcription) controls PARP1 levels, also interacting with STAT3." (PMID 37190289, 2023). "In cervical cancer cell lines, it has been observed that HPV-positive lines have higher levels of STAT3 and pSTAT3 compared to HPV-negative cell lines." (PMID 37372319, 2023). "Cynaroside and Astragalin exert their cervical cancer inhibitory functions by regulating several signaling proteins (e.g., EGFR, STAT3, CCND1, IGFIR, ESR1)." (PMID 38003540, 2023). "The incubation of HeLa cervical cancer cells with PGG markedly decreased their viability, reduced the concentration of cyclin D1 and Bcl-2, and inhibited STAT3 phosphorylation." (PMID 37375411, 2023). "In cervical cancer, once a tumor-suppressor BLCAP is edited, it loses its ability to interact with and inactivate STAT3, thereby increasing cell proliferation." (PMID 36895481, 2023). "The protein levels of the total STAT3 and OSM-induced pSTAT3 were significantly reduced by SD-36 treatment in both cervical cancer cell lines." (PMID 36551576, 2022). "The autocrine activation of IL-6 is responsible for STAT3 phosphorylation in HPV-related malignancies, particularly in cervical cancer." (PMID 36405719, 2022). "External stimuli, such as pro-inflammatory cytokines, can activate the signal transducer and activator of transcription 3 (STAT3) transcription factor, which has been found to be essential for the survival of cervical cancer cells." (PMID 36145459, 2022). "However the role of STAT3 in the autophagy of cervical cancer remains unclear." (PMID 35057825, 2022). "Given that the OSM–OSMR interaction leads to the activation of STAT3 in various cancer cells, we investigated the effect of OSM on STAT3 activity in cervical cancer." (PMID 36551576, 2022). "In cervical cancer, circ-E2F3 inhibits miR-296-5p increasing STAT3 nuclear translocation and upregulates expression of cyclin D1." (PMID 35444695, 2022). "While BLCAP is reported as a novel STAT3 interaction partner in bladder cancer, and A-to-I editing of BLCAP mRNA loses the inhibitory regulation of STAT3 activation in cervical cancer." (PMID 35574370, 2022). "In cervical cancer cells, propofol is able to induce cisplatin-mediated cellular apoptosis through repression of the EGFR/JAK2/STAT3 pathway." (PMID 35517791, 2022). "Reversely, the complementation of miR-125 leads to the decreases in STAT3, MMP-9, MMP-2, and N-cadherin levels and activities, subsequently diminishing the proliferation, metastasis, and inflammation of cervical cancer cells." (PMID 33805515, 2021). "In cervical cancer, HPGD suppresses cell proliferation, migration, and anchorage-independent cell growth by negatively regulating STAT3 and Akt activations." (PMID 33435156, 2021).
cervical carcinoma (continued). "Taken together, STAT3 and HPV E6 constitute a feed-forward circuit that participates in the downregulation of let-7a and miR-125 throughout the development of cervical cancer." (PMID 33805515, 2021). "The pterostilbene is able to reduce expression levels of CD133, Oct4, SOX2, Nanog and STAT3 in impairing CSC features and retarding progression of cervical cancer." (PMID 34769099, 2021). "In cervical cancer, a study has shown that LINC00240 can promote STAT3 expression by sponging miR-124-3p, and then STAT3 can inhibit MICA to reduce the cytotoxicity of NKT cells." (PMID 34425834, 2021). "This indicates that Bazedoxifene inhibits GP130/STAT3 via EMT signaling, a downstream signal in cervical cancer cells." (PMID 34445405, 2021). "In cervical cancer, propofol heightens the cisplatin-triggered cancer cell apoptosis via blocking EGFR/JAK2/STAT3 axis." (PMID 34775376, 2021). "MiR-126 can inhibit the expression of MMP2 by targeting ZEB1, which inhibits the protein expression of p-JAK2 and p-STAT3 and inactivates the JAK2/STAT3 signaling pathway, which inhibits the proliferation, migration and invasion of cervical cancer cells." (PMID 33967611, 2021). "In this study, we investigated the anticancer properties of Bazedoxifene in HPV-positive cervical cancer cells and confirmed that Bazedoxifene inhibits the GP130/STAT3 pathway and suppresses the EMT sub-signal." (PMID 34445405, 2021). "Our recent work, in line with other studies, clearly demonstrated a critical role for STAT3 in driving the expression of critical genes required for the proliferation and survival of HPV+ cervical cancer cells." (PMID 32899142, 2020). "STAT3 and STAT5 probably have the most critical roles in the development of cervical cancer; they are essential for proliferation and survival, in addition to being highly associated with tumor malignancy." (PMID 33076315, 2020). "In human papilloma virus (HPV)-positive cervical cancer cells, fedratinib treatment inhibited JAK2 and STAT3/5 activation, increased apoptosis, and reduced cyclin D1 expression, cell proliferation, and colony formation." (PMID 33521321, 2020). "Promising results for HPV+ cancers have also been obtained: we recently demonstrated that two JAK inhibitors, ruxolitinib and fedratinib, reduced STAT3 and STAT5 phosphorylation, decreased proliferation and induced apoptosis in HPV+ cervical cancer cells." (PMID 32899142, 2020). "In cervical cancer, clinical trials are required to find out whether the use of these molecules can have a positive effect on the overall and disease-free survival of patients, in addition to evaluating the toxicity of these treatments, as the reports indicate that STAT3 inhibitors are highly toxic." (PMID 33076315, 2020). "Rac1-driven activation of STAT3 therefore was shown to stimulate both the proliferation and survival of HPV positive cervical cancer cells, thus highlighting a further example of Rac1 driving upstream activation of STAT3 in cancer." (PMID 32915198, 2020). "In conclusion, the current study indicates that RES inhibits growth of cervical cancer, and EMT and ECM degradation by inhibiting STAT3 Tyr705 phosphorylation." (PMID 33040485, 2020). "We also showed that inhibition or depletion of JAK2 decreases the phosphorylation of STAT5 in addition to STAT3, and that this inhibited the growth of HPV+ cervical cancer cells, similar to the direct inhibition of STAT5." (PMID 32899142, 2020). "This study aims to investigate the role of STAT3 and its phosphorylation in RES‐mediated suppression of cervical cancer." (PMID 33040485, 2020). "Our results collectively demonstrate that pterostilbene can suppress the stem-like properties of cervical cancer cells by downregulating specific CSC markers and STAT3 signaling." (PMID 31935877, 2020).
cervical carcinoma (continued). "Having shown both STAT3 and STAT5 are substrates for JAK2 in HPV+ cervical cancer cells, it was important to understand if the phosphorylation and activation of these proteins correlated during disease progression." (PMID 31817106, 2019). "Pretreatment with TMS-TMF-4f reduced the green fluorescence intensity (IL-6-induced STAT3 phosphorylation) and p-STAT protein levels in both HeLa and CaSki cervical cancer cells." (PMID 31816985, 2019). "The data in this study, and our previous work, demonstrate that JAK2 can activate both STAT3 and STAT5 signalling in HPV+ cervical cancer cells, suggesting that both pathways contribute to the tumourigenesis of these cancers." (PMID 31817106, 2019). "Together, these data demonstrate increased levels of STAT3 expression and phosphorylation in HPV positive cervical cancer cell lines." (PMID 31226168, 2019). "Inhibition of JAK2 using the non-selective compound AG490 has demonstrated that JAK2 activity is required for STAT3 phosphorylation and viral oncogene expression in HPV+ cervical cancer cells." (PMID 31817106, 2019). "We reveal that activation of an IL-6 signalling axis drives the autocrine and paracrine phosphorylation of STAT3 within HPV positive cervical cancers cells and that activation of this pathway is essential for cervical cancer cell proliferation and survival." (PMID 31226168, 2019). "Independent of its direct role in epithelial carcinogenesis, STAT3 may be involved in existence as well as pathological manifestation of HPV16 genome and could be utilized as possible therapeutic, diagnostic and prognostic target for potentially-progressive cervical cancer and pre-cancer lesions." (PMID 31487312, 2019). "In cervical cancer, IL-6 expression promotes tumour proliferation by inducing vascular epithelial growth factor (VEGF)-dependent angiogenesis in a STAT3 dependent manner and has also been suggested as a potential biomarker." (PMID 31226168, 2019). "We have previously demonstrated that inhibition of STAT3 results in the inhibition of proliferation and the induction of apoptosis in HPV positive (HPV+) cervical cancer cells." (PMID 31817106, 2019). "Ectopically expressed STAT3 completely attenuated TMS-TMF-4f-induced apoptotic cell death and PARP cleavage in both cervical cancer cells compared with TMS-TMF-4f-treated control cells." (PMID 31816985, 2019). "As a the new downstream gene of STAT3, our results demonstrated that knockdown of STAT3 or FOXL2 promoted apoptosis and inhibited the growth of cervical cancer cells using RNAi." (PMID 31221094, 2019). "Several studies have demonstrated that abnormal activation of STAT3 and AKT signaling pathways promotes cervical cancer cell proliferation, migration and cell transformation." (PMID 30333561, 2018). "Decreased STAT3 activation results in sensitization to TRAIL-induced apoptosis, even in the TRAIL-resistant cervical cancer cell line SiHa." (PMID 29568369, 2018). "miR-7, miR-9, miR-15, miR-34, miR-99, and miR-125 families participate in MAPK, PI3K-AKT, Jak/STAT3, and mTOR cell-signaling pathways’ regulation as well as in apoptosis, cell cycle, autophagy, and EMT potentiating cervical carcinoma development." (PMID 28216603, 2017). "All of these results suggested that BMX promotes the proliferation of cervical cancer cells by activating the PI3K/AKT/mTOR and STAT3 pathways." (PMID 28514765, 2017). "Conversely, TFF3 knockdown in two cervical cancer cell lines increased CDH1 expression mRNA level with concomitant decrease of phosphorylation of STAT3." (PMID 28070169, 2017). "STAT3 and ABL2 augment proliferation, G2/M cell cycle transition, migration, invasion, and tumor growth in cervical cancer." (PMID 28216603, 2017). "Further studies revealed that BLCAP interacted with signal transducer and activator of transcription 3 (STAT3) and inhibited its phosphorylation, while A-to-I RNA editing of BLCAP lost the inhibition to STAT3 activation in cervical cancer cell lines." (PMID 28455960, 2017).
cervical carcinoma (continued). "On the other hand, another study assessed the functional contribution of Let-7a and miR-21, which interact with STAT3 signaling and/or its downstream effects in HPV16-positive cervical cancer cells." (PMID 26975392, 2016). "Our results clearly indicate that Cucurbitacin D targets both STAT3 and HPV E6 in cervical cancer cells." (PMID 27824155, 2016). "Taken together, these findings suggest the existence of a functional circuit involving Let-7a, STAT3, miR-21 and PTEN in cervical cancer cells." (PMID 26975392, 2016). "The results showed that the increment in the PRL-mediated phosphorylation of STAT3 in the cell lines HeLa, SiHa and C-33 A was detectable 48 h after treatment and that co-stimulation with the AG490 reduced this effect in the three cervical cancer cell lines." (PMID 26346346, 2015). "This indicated an option to deprive the activated IL-6/STAT3 network against inflammation including fibroblast senescence in tumor microenvironment which may be considered as a complement to increase the efficacy of the targeted therapy against HPV 16/18 in cervical cancer." (PMID 26308848, 2015). "Signal transducer and activator of transcription 3 (STAT3) is an oncogenic transcription factor constitutively active and aberrantly expressed in cervical cancer." (PMID 23874455, 2013). "Both HPV positive cervical cancer cell lines as well as HSIL and cancer tissues expressed high levels of STAT3 transcripts." (PMID 20977777, 2010). "We also showed that expression of a dominant-negative Stat3 mutant and a JAK/Stat3 small molecular inhibitor, JSI-124, induced apoptosis in HeLa and SiHa human cervical cancer cell lines expressing elevated levels of phosphorylated Stat3." (PMID 17311011, 2007). "Since Stat3 phosphorylation at Tyr705 is elevated in cervical and endometrial cancer tissues and Stat3 pathway has been shown to participate in oncogenesis, we examined whether the inhibition of Stat3 pathway by dnStat3 in cervical cancer cells could suppress cancer cell growth." (PMID 17311011, 2007). "Furthermore, they found that JAK2 phosphorylation correlates with both STAT3 and STAT5 phosphorylation, highlighting JAK2/STAT3 and JAK2/STAT5 are functional in cervical cancer cell." (PMID 41516206, 2025). "Whereas in cervical cancer, MEG3 was reported to promote apoptosis and inhibit cell proliferation via binding to p-STAT3, which resulted in the ubiquitination and degradation of STAT3." (PMID 40548301, 2025). "Although there is biological evidence, the clinical impact of M2-TAM’s pro-tumor activity and via STAT3 and NF-κB signaling pathways on the overall survival of cervical cancer patients has not been clarified." (PMID 39061137, 2024). "Our results showed that CD163 + CD204 + M2-TAM via STAT3/NF-κB signaling pathways was strongly responsible for increasing protein factors of EMT and invasion (MMP9), reverberating in a worse prognosis scenario in patients with cervical cancer." (PMID 39061137, 2024). "Research showed that root extract of P. vulgaris inhibited 12 signaling pathways in a cervical cancer cell line and the most potent activation inhibition was observed for MYC, Notch, Wnt, E2F, Ets, Stat3, Smad, Hdghog, AP-1, and NF-κB, at a concentration of 40 μg/mL." (PMID 36674653, 2023). "Hpgd (15-hydroxyprostaglandin dehydrogenase) encodes a member of the short chain nonmetallic enzyme alcohol dehydrogenase protein family, and can activate STAT3 and AKT pathways to promote proliferation, migration and anchorage-independent growth of cervical cancer cells." (PMID 37055764, 2023).